IL4R (interleukin 4 receptor)
Diseases named in the same sentence as IL4R in open-access papers (continued):
Sharing a sentence is not in itself a finding about the gene and the disease.
infection (continued). "major infection, we checked whether the higher numbers of infected cells could be due to increased numbers of these cells overall, as a consequence of IL-4Rα-deficiency." (PMID 32039054, 2019). "IL-4Rα–activated Mφs are known to mediate tissue repair in the skin but also control airway inflammation and hemorrhage following the acute lung injury caused by primary infection with lung-migrating nematodes." (PMID 31586037, 2019). "The fact that 50% of B cell deficient mice succumbed to disease at the beginning of the chronic stage of infection suggests that the mechanism of death may be different from that operating in B cell-specific IL-4Rα-deficient mice." (PMID 30619289, 2018). "Levels of total IgG1 and IgE increased significantly in mice of all genotypes after infection with C. neoformans, except for IgE levels in IL-4Rα-deficient mice, which are unable to produce IgE20, underlining the overall Th2-biased immune response to this pathogen." (PMID 29422616, 2018). "Physiologically relevant levels of recombinant Ym1 observed in the BAL during N. brasiliensis infection and lung inflammation, was delivered to IL-4Rα-deficient animals at the time when repair in wild-type mice would usually occur (days 4 and 5) and responses were examined at day 6 post-infection." (PMID 30500858, 2018). "In an attempt to analyze if early after L. major inoculation, IL-4 secretion by keratinocytes could act in an autocrine way on these cells locally during the first days of infection, we generated mice genetically deficient in the IL-4Rα on keratinocytes." (PMID 29067025, 2017). "However, liver egg burden was similar between the different groups, ruling out a differential level of infection as the cause of the observed diminished type-2 responses in iCre-/+IL-4Rα-/lox Tam2 and IL-4Rα-/- mice." (PMID 28827803, 2017). "As expected, most of IL-4Rα deficient mice (70%) succumbed prematurely to infection with 35 S." (PMID 28827803, 2017). "As impaired viability of S. mansoni-infected mice following IL-4Rα knockdown at 6 weeks post-infection (Tam6) was observed, the associated immune and histopathological responses of Tam6-fed RosaCreERT2-/+IL-4Rα-/lox mice (termed iCre-/+IL-4Rα-/lox Tam6) was investigated." (PMID 28827803, 2017). "Immunity to challenge infection was compromised in IL-4Rα- and IL-25-deficient mice, despite levels of specific antibody comparable to immune wild-type controls, while deficiencies in basophils, eosinophils or mast cells or CCR2-dependent inflammatory monocytes did not diminish immunity." (PMID 25816012, 2015). "In addition to antigen presentation we also demonstrate IL-4Rα-dependent increases in IL-13 production by endogenous B cells to be associated with control of secondary infection." (PMID 24204255, 2013). "In addition, IL-4−/− and IL-4Rα−/− BALB/c mice are more susceptible to infection with L. donovani and also experimental visceral leishmaniasis in C57BL/10 mice is independent of IL-4 and the associated Th2 immune response." (PMID 23825956, 2013). "In the IL-4Rα┴ mice there is a decrease/decline in methylation levels at the IL-4R gene promoter or associated CpG islands which could result in the inhibition of the IL-4R and infection." (PMID 40977748, 2025). "A hallmark of anti‐parasite type 2 immunity is the IL‐4 receptor (IL‐4Rα, essential for IL‐4 and IL‐13 downstream signaling) mediated activation of macrophages and the resulting M(IL‐4) activation phenotype, which has been associated with many crucial features of resistance to infection." (PMID 31267552, 2019). "Therefore, IL-4R−/−/IL-5−/− signalling may also be essential for the control of infections with human pathogenic filariae." (PMID 31109364, 2019). "To test whether IL-25-mediated promotion of immunity to primary H. polygyrus infection was entirely dependent upon IL-4Rα, or could mediate an IL-4Rα-independent mode of protection, we administered exogenous IL-25 from days 14–17 of infection to Il4ra-deficient mice." (PMID 30238872, 2018).
infection (continued). "In BALB/c mice, susceptibility to infection with the intracellular parasite Leishmania major is driven largely by the development of T helper 2 (Th2) responses and the production of interleukin (IL)-4 and IL-13, which share a common receptor subunit, the IL-4 receptor alpha chain (IL-4Rα)." (PMID 24204259, 2013). "There was a significant decrease in body weight of the untreated WT mice at week 2 and of the IL-4Rα┴ mice at week 1 post-infection." (PMID 40977748, 2025). "In the HPC both WT and IL-4R┴ had elevated CXCL-10 following infection and decreased CXCL-10 after Iloprost treatment compared to untreated infected mice." (PMID 40977748, 2025). "Ornithonyssus bacoti mites were fed on untreated and DR-treated microfilaremic Il4rα-/-/Il5-/- mice at 70 days post-infection (dpi)." (PMID 40644522, 2025). "While 100% of T. crassiceps-infected IL-4Rα+/+ (WT) mice harbored large parasite loads, more than 50% of th eIL-4Rα−/− mice resolved the infection." (PMID 38392907, 2024). "At 5, 7, and 10 days after infection, Il4rα mRNA transcript levels were gradually decreased in the spleen, suggesting that L. monocytogenes infection downregulates Il4rα expression." (PMID 39483462, 2024). "The TRMs from the eoCre: Il4/13f/f mice displayed significantly lower expression of Mrc1, Ccl24, and Tslp than WT mice after infection, whereas Il4r expression remained unchanged." (PMID 38030609, 2023). "The lung is a crucial site in priming protective immunity against N. brasiliensis where lung-resident CD4+ T cells elicit IL-4Rα dependent protection against secondary infection." (PMID 35264261, 2022). "As a conclusion, the infection of Il-4rα-/-/Il-5-/- mice highlights the subtle balance necessary to control infections while maintaining tissue homeostasis." (PMID 36353644, 2022). "Consistent with previous studies, Il-4rα-/-/Il-5-/- mice had a higher worm burden in the pleural cavity in the patent phase of infection (70 dpi)." (PMID 36353644, 2022). "IL-4 and IL-13 share a common receptor, IL-4Rα, whose effects in CL have been widely studied in L. major infection and to some extent during L. mexicana infection." (PMID 35154068, 2021). "The MFI of Ym1 on CD11c+CD11b- cells and CD11c+CD11b+ cells was significantly lower in IL-4Rα−/− neonates at all days examined post-infection." (PMID 34682248, 2021). "TNFα peaked in the BALF of both strains of mice at day 27 post-infection, however, this cytokine was observed at lower levels in the IL-4Rα−/− neonates." (PMID 34682248, 2021). "This increase in specific antibody at days 34 and 41 post-infection corresponded to reduced P. murina burden in the lungs of IL-4Rα−/− pups." (PMID 34682248, 2021). "To investigate the effect of IL-4Rα mAb intervention in the context of allergic sensitization and pH1N1 infection, we measured viral load and the innate antiviral response in a time-course manner." (PMID 33653328, 2021). "In contrast to RELMα, PD-L2 expression on macrophages post infection was dependent on IL4Rα signalling in the macrophages." (PMID 34329367, 2021). "While IFNγ increased in the BALF of both strains of mice at day 27 post infection, it tended to be at higher levels in the IL-4Rα−/− neonates." (PMID 34682248, 2021). "Fifty percent of wild type mice had detectable P. murina within their lungs through day 41 post-infection while IL-4Rα−/− neonates completely cleared infection by day 35 post-infection." (PMID 34682248, 2021). "In contrast to anti-cryptococcal IgG levels, anti-cryptococcal CPS and protein IgM titers were unaffected by progression of the infection, with exception of elevated anti-Cn IgM levels in WT and IL-4Rα-/- mice on day 42 post infection." (PMID 34367172, 2021). "Using our model of HDM-sensitization and pH1N1 infection, mice were subjected to a mAb targeting murine IL-4Rα through a prophylactic as well as a therapeutic treatment strategy." (PMID 33653328, 2021).
infection (continued). "We suggested that IL-4Rα, smooth muscle cell-dependent cytokine production contributes to the initial recruitment of immune cells and initiating Th2 immunity to infection." (PMID 32410852, 2020). "In two of the groups of animals, one with blocked IL-4Rα and one with rIL-13Rα2 treatment prior to infection, a significant reduction in STAT6 phosphorylation and translocation was observed at 2 wppi compared with the to rIL-25-treated control animals." (PMID 33276813, 2020). "mf production was only detected in 2/9 mice at 11 wk in 2/3 mice with active adult infection, indicating that sterile cure of adult B. malayi had occurred in the majority of IL-4Rα−/− mice at a point prior to establishment of fecund infections." (PMID 32571840, 2020). "In the minority of IL-4Rα−/− mice featuring active fecund infection, yields of mf produced were lower, either reflecting an indirect effect of reduced adult burdens or, alternatively, that IL-4Rα–independent processes were also directly affecting mf survival." (PMID 32571840, 2020). "Further, B. malayi fecund infections were evident in (7/11) IL-4Rα−/−CCR3−/− mice versus 4/11 IL-4Rα−/− mice and 1/10 WT mice." (PMID 32571840, 2020). "As MIF-deficient mice mounted a normal adaptive B- and T cell response to infection, we concluded that these mice must lack a key innate effector population, which we propose are the IL-4R-dependent M2 macrophages." (PMID 31708913, 2019). "Altogether, these data indicate that IL-4Rα signaling on T cells transiently exacerbates infection in the liver after infection with L. donovani." (PMID 31475014, 2019). "Platelet activation as measured by P-selectin on platelets was similar between mice strains during infection, platelet neutrophil-complexes were reduced in IL4R/GPIbα compared to controls (P < .01 vs controls)." (PMID 30312422, 2019). "Upon secondary infection, IL-4Rα–activated Mφs act in cooperation with antiparasitic neutrophil, eosinophil, type 2 innate lymphoid cell, and memory Th2 cell responses to mediate parasite control." (PMID 31586037, 2019). "In the present study we directly compared the impact of IL-4R, IL-5, eosinophils (dblGATA) and both IL-4R + IL-5 on the infection with the filarial nematode L. sigmodontis." (PMID 31109364, 2019). "In contrast, experimental studies using gene-deficient mice in L. donovani infections have indicated that the control of not only primary infection, but also successful chemotherapy and successful vaccination is IL-4, IL-13, and IL-4Rα signaling-dependent." (PMID 31475014, 2019). "In our study, pSTAT6, IL-4Rα, and IL-13Rα1 were significantly increased following infection with S. japonicum." (PMID 31886304, 2019). "L. donovani-specific IgG1 and IgG2a levels and total serum IgE levels were measured in CD4+ T cell specific IL-4Rα−/− mice, wild-type control and global IL-4Rα−/− mice at days 15, 30, and 56 post-infection." (PMID 31475014, 2019). "Surprisingly, IL-4Rα-independent expression of RELMα and Ym1 was observed in all cell types examined, with the exception of MoDCs, whereby infection-induced Ym1 was strongly IL-4Rα-dependent." (PMID 30500858, 2018). "In contrast, mb1creIL-4Rα−/lox mice developed significantly increased levels of IL-4, IL-10, IL-6, IL-17, and IFN- γ compared to IL-4Rα−/lox littermate control mice at 24 weeks post infection." (PMID 30619289, 2018). "L. major LV39-infected KRT14cre IL-4Rα−/lox BALB/c mice showed significantly fewer parasites at the site of infection (the ear) than the littermate control IL-4Rα−/lox BALB/c mice." (PMID 30275010, 2018). "Collectively, the data suggest that systemic antibody responses in KRT14cre IL-4Rα−/lox BALB/c mice were unaffected by the deletion of the IL-4Rα signaling receptor on keratinocytes during subcutaneous infection with L. major IL-81 in the footpad." (PMID 30275010, 2018). "As expected, IL-4Rα-/- mice showed enhanced tissue damage, coinciding with a failure to repair the lungs following infection." (PMID 30500858, 2018).
infection (continued). "We found that following subcutaneous infection of Foxp3cre IL-4Rα−/lox and IL-4Rα−/lox littermate control mice with Nb, the airways of Nb-infected Foxp3cre IL-4Rα−/lox mice showed much heavier mucus production 9 d post infection." (PMID 30379806, 2018). "Global IL-4Rα−/− BALB/c mice had significantly smaller lesion diameters and lower parasite loads in the ear than littermate control IL-4Rα−/lox BALB/c mice after infection with L. major IL-81." (PMID 30275010, 2018). "In the present study, we show that Foxp3+ Treg cells in secondary lymphoid organs constitutively express IL-4Rα and up-regulate the receptor expression upon S. mansoni (Sm) infection." (PMID 30379806, 2018). "Our results revealed that innate IL-4Rα-independent Ym1 plays a role in initiating an appropriate type 2 response that occurs later during infection." (PMID 30500858, 2018). "We have recently shown that interfering with IL-4Rα signaling during the chronic phase of infection can ameliorate fibrogranulomatous pathology and reduce tissue scarring without being detrimental to host survival during chronic schistosomiasis." (PMID 30619289, 2018). "Together, these data showed that IL-4Rα contributes to the recall and maintenance of optimal type 2 immune responses during secondary infection with N. brasiliensis in mice." (PMID 28651009, 2017). "Administration of tamoxifen prior to secondary infection successfully reduced the expression of IL-4Rα on mediastinal lymph node (mdLN) CD4+ T cells in iCre-/+IL-4Rα-/Lox mice compared to control that were given vegetable oil." (PMID 28651009, 2017). "A significant reduction of CD4+ and CD8+ T lymphocytes in the MLN of S. mansoni-infected iCre-/+IL-4Rα-/lox Tam16 animals at week 18 post infection was observed." (PMID 28827803, 2017). "Our present findings, using our model of inducible IL-4Rα deletion where IL-4Rα is only removed from infected mice prior to secondary infection argues for a contributing role of IL-4Rα in the memory Th2 response during secondary N. brasiliensis infection." (PMID 28651009, 2017). "A significant reduction of T lymphocytes in the MLN of S. mansoni-infected iCre-/+IL-4Rα-/lox Tam6 animals at week 7 post infection was observed." (PMID 28827803, 2017). "In line with the elevated levels of IFNγ detected at the site of infection and in dLN cells, high levels of serum IgG2c were observed in KRT14CreIL-4Rα−/lox and control IL-4Rα−/lox mice." (PMID 29067025, 2017). "brasiliensis L3 and IL-4Rα expression was timely impaired between day 6 and day 7 post infection after an optimal Th2 immune responses has already been established as indicated in our kinetics study, by administering tamoxifen day 5 post infection onwards." (PMID 28651009, 2017). "Of interest, regulatory B cell frequencies increased during infection and particularly in infected iCre-/+IL-4Rα-/lox Tam16 mice amid a rather stable total count in S. mansoni-infected iCre-/+IL-4Rα-/lox Tam16 animals when compared to littermate controls." (PMID 28827803, 2017). "Upon infection with L. major i.d. in the ear pinna with a low or with a higher dose of parasites, mice with impaired IL-4Rα signaling on keratinocytes were able to resolve their cutaneous lesion, develop protective Th1 cells, and control parasite load." (PMID 29067025, 2017). "As of yet, our findings of remnant gut worms following IL-4Rα knockdown prior to secondary infection strongly suggests that IL-4Rα mediated signaling also contributes to build a more efficient protective immunity against N. brasiliensis." (PMID 28651009, 2017). "Bleeding was visible in the gut of the animals that rapidly succumbed to infection following removal of IL-4Rα." (PMID 28827803, 2017). "Interrupting IL-4Rα expression prior to the secondary infection resulted in reduced proportions and total numbers of CD4+CD44+ T cells expressing Gata-3 compared to control mice given vegetable oil." (PMID 28651009, 2017).
infection (continued). "As infection progressed, a decrease in the number of goblet cells was also observed in the IL-4R KO mice compared to naïve and IL-4 KO mice." (PMID 28192541, 2017). "In our study, IL-4Rα removal during primary and secondary N. brasiliensis infections led to a drastic reduction of mucus production in the gut (primary infection) and lungs (secondary infection)." (PMID 28651009, 2017). "In this study, we found that T reg cells were actively phosphorylating STAT6 during infection and that IL-4R signaling was required for the conversion of T reg cells to Th2 cells in vitro and in vivo." (PMID 28507062, 2017). "Tamoxifen-induced knockdown of the IL-4Rα after egg deposition during the chronic phase (16 weeks post-infection) uncovered a hitherto unappreciated facet of the IL-4Rα mediated type 2 responses." (PMID 28827803, 2017). "To investigate a putative autocrine role of IL-4 signaling on keratinocytes at the site of infection, we generated C57BL/6 mice deficient for IL-4Rα expression selectively in keratinocytes." (PMID 29067025, 2017). "The findings above demonstrated an impaired viability of S. mansoni-infected mice following IL-4Rα knockdown at 2 weeks post-infection (Tam2)." (PMID 28827803, 2017). "Liver egg burden was similar between the control IL-4Rα-/lox, ruling out a differential level of infection between both groups of mice." (PMID 28827803, 2017). "Host control of N. brasiliensis recall infection is dependent on IL-4Rα-dependent macrophage polarization to the alternatively activated phenotype in the lung." (PMID 26900854, 2016). "WT, IL-4/IL-13-/- mice and IL-4Rα-/- mice were infected with N. brasiliensis and, at 5 days post-infection, SP-D levels in BAL fluid and serum were quantified." (PMID 26900854, 2016). "Numbers of NK cells increased significantly in most GKO strains following infection with the mutant virus except for WT and IL-13−/−/IL-4Rα−/− mice." (PMID 25751266, 2015). "Here we characterized the IL-4Rα expression by flow cytometry in the lungs during low dose H37Rv infection." (PMID 25790379, 2015). "Together these studies show that immunization with secreted products from a gastrointestinal helminth induces long-lived sterile immunity against challenge infection through IgG1 antibodies acting in parallel with IL-4Rα- and IL-25-dependent effector cells." (PMID 25816012, 2015). "The increased number of intestinal granulomas in IL-6−/− mice also indicated potentiation of type 2 responses early in infection, as these are foci of alternatively activated macrophages, which form in an IL-4Rα-dependent manner." (PMID 24185641, 2014). "Further, both macrophage proliferation and numbers are reduced in IL-4−/− and IL-4Rα−/− mice in all infection models tested, emphasizing the central role of IL-4 in driving macrophage accumulation during infection." (PMID 25319331, 2014). "In experimental models of S. mansoni infection it has been shown that the responsiveness through the IL-4Rα is important to granuloma formation and survival of the host during infection." (PMID 24757288, 2014). "Naïve WT mice show similar expression of CCL2 and CCL20 as compared with naïve IL-4Rα−/− mice, and for both naïve genotypes the levels are considerably lower than upon infection with C. neoformans." (PMID 24475277, 2014). "This beneficial role of early IL-4Rα function is intriguing as wild-type (WT) mice that are protected in the initial phase of infection show features of an otherwise type 2-biased immune response." (PMID 24475277, 2014). "The unexpected finding of lower fungal lung burdens in WT mice compared to IL-4Rα−/− mice indicates protective effects of IL-4Rα signaling during the onset of immune responses triggered by the infection." (PMID 24475277, 2014). "Because actual IL-4Rα deletion occurred only early in infection, the data suggest AAMΦ act at early stages of infection to influence later resistance." (PMID 25319331, 2014).